CLDN5 (claudin 5)
Diseases named in the same sentence as CLDN5 in open-access papers (continued):
Sharing a sentence is not in itself a finding about the gene and the disease.
tumor (continued). "Four primary cell populations were first identified using canonical cell markers: WT tumor cells (WT1, NCAM1, SIX1, SIX2, PAX2), cancer-associated fibroblasts (CAFs) (ACTA2, TAGLN, COL1A1, PDGFRB), endothelial cells (PECAM1, CLDN5, ENG, VWF) and immune cells." (PMID 40098972, 2025). "Clustering analysis of tumor cells revealed six subclusters exhibiting transcriptional heterogeneity, including Cp+, Cldn5+, Crabp1+, Ebf1+, Ptprc+, and Srgn+ tumor cells." (PMID 39979981, 2025). "The results found only CD34+CLDN5+ cells were observed to be P16+P21+ and γH2AX+ positive, which prompted that the CD34+CLDN5+ ECs were senescent phenotype in tumor tissue." (PMID 39674501, 2025). "Other genes such as ABCB5, CLDN5, RCC1 have also been implicated in CRC-related processes, with several studies suggesting their potential value in tumor diagnosis, progression monitoring, or prognostic evaluation." (PMID 40893943, 2025). "Together, these findings indicate the pivotal role of Cldn5 in maintaining endothelial barrier integrity and highlight its therapeutic potential in limiting tumor progression and metastasis." (PMID 40940757, 2025). "The results showed the presence of CD34+CLDN5+ positive cells in tumor tissue, while these cells were scarcely observed in peri-tumor tissue." (PMID 39674501, 2025). "Among them, MMP-2 and MMP-9 blocked the expression of tight junction proteins claudin-5 and ZO-1, thus helping tumor cells to cross the BBB." (PMID 38243240, 2024). "The disruption of endothelial continuity is initiated by a tumor-derived cANGPTL4 through direct interaction with integrin α5β1, VE-cadherin, and Claudin-5 in a temporally sequential manner." (PMID 38233877, 2024). "The image results showed that the distributions of VE-cadherin, JAM-A and claudin-5 became discontinuous and vastly diminished in hBMVEC monolayers treated with conditioned medium derived from tumor cells with relatively high expression of MSLN." (PMID 38570866, 2024). "Tumor cells have the capacity to generate MMP-2 and MMP-9, which inhibit the expression of tight junction proteins like claudin-5 and ZO-1, consequently causing disruption to the BBB." (PMID 38243240, 2024). "The expression of CLDN5 was strongly linked with that of immune checkpoint genes, such as TGFβ1, C10orf54, and ADORA2A in most tumor types, including STAD, COAD, and ESCA." (PMID 37286335, 2023). "Tumor purity, another substantial parameter for the tumor microenvironment, is negatively correlated with CLDN5, CLDN11, and CLDN18 (Absolute value of Spearman Correlation is 0.20 and p < 0.001)." (PMID 37799140, 2023). "There were significant differences in CLDN5 expression in tumorous tissues and normal tissues, as indicated by the results (P< 0.05)." (PMID 37286335, 2023). "Intact tumor-associated vasculature of the GEMM model of SHH MB displayed organized, linear expression of junctional markers CD31 and CLDN5, outlining a continuous vessel structure with extensive astrocytic encircling." (PMID 36776301, 2023). "The results suggest that CLDN5 can be used as a biomarker for tumor diagnosis and prognostic impact." (PMID 37286335, 2023). "These MMPs secreted by metastasizing tumor cells damage the integrity of the BBB by disrupting tight junctions shaped by Claudin-5, creating space for the invasion of cancer cells." (PMID 38072918, 2023). "The GTEx and TCGA databases were used to analyze CLDN5 expression in multiple tumor types and normal tissues." (PMID 37286335, 2023). "The results suggested that CLDN5 expression was reduced in the tumor compared with that in para cancer, with a decrease in the mean optical density (P<0.01)." (PMID 37286335, 2023). "In some images, both ZO-1 and Claudin-5 structures withing BMECs were seen to colocalized with tumor cells, indicating the proximity of BMECs to the tumor cells in vivo." (PMID 35351947, 2022).
tumor (continued). "Treatment with the proper dose bevacizumab increases claudin‐5 (CLDN5) expression to decrease tumour invasion and metastatic potential." (PMID 35224833, 2022). "We showed that the expression of WNT5A was low in icSFT/HPC and the level of CLDN5 protein, which constitutes a tight junction, was reduced in tumor vessels in icSFT/HPC." (PMID 33799999, 2021). "Regarding the markers used in our study, Claudin-5 is a member of the Claudin protein family and may be directly or indirectly related to tumor motility and neovascularization, facilitating metastasis and tumor progression because it is closely linked to epithelial and endothelial cells." (PMID 34438863, 2021). "The dysfunction of claudin-5 protein was related to endothelial permeability in a series of pathological processes, including inflammation, tumor edema, toxic damage, and high glucose damage." (PMID 34437417, 2021). "As the oncogenesis of SFT/HPC is associated with angiogenesis, maintaining the mechanical stability of tumor vessels is more difficult in icSFT/HPCs than exSFT/HPCs due to the decreased expression of CLDN5 and WNT5A." (PMID 33799999, 2021). "To evaluate the impact of HOXB9 expression in tumor cells on junctional proteins involved in endothelial barrier function, we examined the expression of ZO-1, claudin-5, and VE-cadherin in HUVECs after co-culture with tumor cells." (PMID 33411683, 2020). "Claudin-5 in endothelial cells promotes vascular permeability and angiogenesis leading to metastasis in tumor cells." (PMID 33004792, 2020). "From day 10 to 21, the level of claudin-5 continued to decrease further in the tumor group of mice, while it was restored to the normal level in the sham group of mice." (PMID 32796132, 2020). "On the other hand, VE-cadherin was shown to be a direct target of miR-101 in the tumor cells and the brain endothelium, and expression level of claudin-5 was found to be governed by that of VE-cadherin." (PMID 32645833, 2020). "While a decrease in occludin, zonula occludens, and claudin-5 expression was measured in the sedentary mice, an increase in claudin-5 expression and unchanged occludin and zonula occludens levels were found in the exercising mice 48 h post tumor injection." (PMID 31936342, 2020). "It should be noted that the tumour-covered endothelium still showed a continuous claudin-5 staining, indicating the presence of complete TJs in the absence of the perivascular astrocyte sheath." (PMID 31426859, 2019). "SNX27 KD significantly reduced the amount of Claudin-5 and decreased the cell-to-cell tight junctions that made the tumor cells “glue” together." (PMID 31182056, 2019). "claudin-5, in various pathological tumor processes, regulated the change in endothelial or epithelial permeability, exercising a protective role of BBB to maintain its integrity." (PMID 30680070, 2018). "In various pathological processes, including inflammation, edema, toxic damage, trauma and tumor, claudin 5 regulates the change in endothelial or epithelial permeability." (PMID 30680070, 2018). "The data obtained in this study demonstrated that the regulation of Dkk-3 confirmed the caspase-mediated apoptosis involvement in tumorigenesis process while the modulation of claudin-5 highlited the role of BBB to maintain its integrity in tumor environment." (PMID 30680070, 2018). "The expression of PKCα, ZO-1, occludin and claudin-5 in tumor microvessel segments was detected by Real-time PCR assay." (PMID 29311822, 2017). "In various pathological processes, including inflammation, edema, toxic damage, trauma and tumor, claudin-5 regulate the change in endothelial or epithelial permeability." (PMID 28978116, 2017). "In the peritoneal vasculature of tumor patients VE-Cadherin and claudin 5 protein are clearly down-regulated as indicated by an unevenly distributed staining." (PMID 26868378, 2016). "Histamine significantly decreased the protein levels of ZO-1, occludin, and claudin-5 in endothelial and tumor cells." (PMID 27121317, 2016).
tumor (continued). "Differences in VEGF levels, VE-cadherin and claudin 5 gene expression were analyzed in relation to various tumor characteristics (tumor stage, grading, histological subtypes, resection status after surgery) and then compared to controls." (PMID 26868378, 2016). "The expression of HSF2, ZO-1, occludin and claudin-5 in tumor microvessel segments was detected by Real-time PCR assay." (PMID 26078353, 2015). "The staining was used to assess the location, distribution and the degree of staining of Claudin-5 in tumour and normal/background samples." (PMID 22559840, 2012). "When comparing the levels of Claudin-5 against tumour grade, little difference in expression was observed (p ≤ 0.85)." (PMID 22559840, 2012). "Patients whose tumours expressed high levels of Claudin-5 had shorter survival than those with low levels (p = 0.004)." (PMID 22559840, 2012). "The staining for Claudin-5 within the tumour sections was however, decreased in both endothelial and epithelial cells." (PMID 22559840, 2012). "However, within BM cores, rather than margins, tumor-adjacent endothelial cells exhibited lower claudin-5 expression compared with tumor-avoiding endothelial cells, supporting a model of vascular co-option during BM colonization." (PMID 39998776, 2025). "Emerging evidence also links Cldn5 to modulation of the tumor–immune microenvironment." (PMID 40940757, 2025). "Conversely, enhancing Cldn5 expression can reinforce barrier integrity and suppress tumor invasion." (PMID 40940757, 2025). "High-dose bevacizumab reduces CLDN5, increasing tumor invasion." (PMID 40687428, 2025). "In order to illustrate the mechanism by which the senescent ECs recruit MSCs into TME, we further analyzed our sc-RNA seq data and noticed that the CD34+CLDN5+ECs may recruit the MSCs into the tumor tissue by IGF system." (PMID 39674501, 2025). "Cldn5 inhibition lead to an increase in vascular permeability to gadolinium across the brain, with a noticeable increase in CD8α+ cell influx into the tumor microenvironment." (PMID 40408475, 2025). "For the EC-related genes in this module, it has been established that theCLDN5 gene is expressed in both endothelial and epithelial cells, and that the reduction of CLDN5 would decrease intercellular adhesion, leading to incomplete vascular endothelium and promotion of tumor metastasis [52‒54]." (PMID 38186223, 2024). "We treated brain endothelial cells with conditioned medium from brain metastatic cells and found that knockdown of MSLN inhibited the degradation of VE-cadherin, JAM-A and claudin-5 on brain endothelial cells, significantly reducing the number of tumor cells migrating across the endothelial layer." (PMID 38570866, 2024). "Both within and outside the tumor, increased Ki67 expression related to microvascular proliferation and inhibited connexin claudin-5 expression related to vascular permeability in endothelial cells engender a mutually beneficial coexistence between the tumor and the vessels within the BME." (PMID 38104104, 2023). "A GEO dataset, GSE49051, was downloaded from the database to determine whether CLDN5 expression was related to tumor." (PMID 37286335, 2023). "Another study found that elevated levels of VEGF promote tumor growth and facilitate the spread of neoplastic cells in the abdominal cavity diminishing endothelial cell adhesion (VE-cadherin and Claudin 5), thus increasing vascular permeability and ascites production." (PMID 36611458, 2023). "Although only a small proportion of tumor cells showed increased MMP9 expression and tumor vessels showing decreased CLDN5 expression and low vascular tightness were distributed occasionally, extracranial metastasis likely occurs at a low frequency after a latent period of several years." (PMID 33799999, 2021).
tumor (continued). "Based on the known annotation of marker genes from the literature, we grouped cells of nine clusters into four cell types: GNP-like tumor cells (expressing Math1 and Grin2b), microglia (expressing Aif1 and Cd68), T cells (expressing Cd3d and Cd3e), and endothelial cells (expressing Cldn5 and Cdh5)." (PMID 34210306, 2021). "While expression of the tight-junction gene CLDN5 was similar in Pe1 ECs and Co1 ECs, some adherens junction mRNAs, including VE-cadherin (encoded by CDH5) and CD31, were upregulated in ECs in the tumor core compared with peripheral ECs." (PMID 34228647, 2021). "Downregulation of claudin-5 increased the permeability of the blood–tumor barrier, suggesting it could prevent brain metastasis." (PMID 33714203, 2021). "In contrast to upregulation of PLVAP in Co1 ECs, the expression of tight-junction molecules, including CLDN5, was similar between ECs in the periphery and tumor core, highlighting an important role of transcellular pathways for BBB breakdown and the edema formation observed in GBM." (PMID 34228647, 2021). "Survival analysis showed that the patients with low expression of Claudin-5 had higher survival percentage, indicating that Claudin-5 might be a tumor promoter." (PMID 30874545, 2019). "The aim of this study was to determine the role of Wnt pathways in the regulation of tumor growth, apoptosis process by targeting Dkk-3, tight junctions alteration involving claudin-5, suggesting possible therapeutic interactions involving Wnt/Toll-like receptors (TLRs) pathways." (PMID 30680070, 2018). "To better understand if the gene deficiency of TLR-4 could increase the expression of Dkk-3, we made an immunoistochemical analysis of Dkk-3 and claudin-5 on tumor sections." (PMID 30680070, 2018). "Similarly, claudin-5 expression was moderately lower in patients with tumor, while healthy people significantly expressed high claudin-5 levels." (PMID 30680070, 2018). "In various pathological processes, including inflammation, trauma and tumor, claudin 5 regulate the change in endothelial or epithelial permeability, therefore, modification in claudin-5 expression may play a role in malignant transformation." (PMID 28978116, 2017). "The levels of Claudin-5 were also analysed against tumour-node-metastasis (TNM)." (PMID 22559840, 2012). "Furthermore, patients whose tumours expressed high levels of Claudin-5 had significantly shorter survival than those with low levels of expression of Claudin-5." (PMID 22559840, 2012). "Regulation of claudin 5 expression by cadherin 5 may therefore reinforces such crosstalk between tight and adherens junctions to promote tumor growth and metastasis." (PMID 19812696, 2009). "However, in other contexts, such as retinal inflammation, tumor microenvironments, or aging, excessive Cldn5 expression may contribute to pathology by excessively tightening barriers, limiting immune surveillance, or altering endothelial plasticity." (PMID 40940757, 2025). "Similarly, the CD34+CLDN5+ cells were existed in tumor samples of patient." (PMID 39674501, 2025). "Mechanistically, tumor progression often involves epithelial–mesenchymal transition (EMT), during which epithelial markers like Cldn5 are downregulated." (PMID 40940757, 2025). "Several hub genes, such as CDH5, CLDN5, VWF, and PECAM1, were significantly upregulated, reflecting their established involvement in vascular development and tumor progression." (PMID 41008787, 2025). "In the tumor microenvironment, tumor cells secrete factors such as VEGF, TGF-β1, and ANGPTL4 to downregulate claudin-5 and ZO-1, thereby weakening the endothelial barrier." (PMID 40574854, 2025). "In summary, we identified a novel subset of CD34+CLDN5+ECs, with distinct senescent cellular features and high expression of IGF2, which was regulated by CEBPβ, primarily existed in the HCC tumor tissue." (PMID 39674501, 2025).
tumor (continued). "Together, these results identified that the CD34+CLDN5+ cells (cluster 11) as a subtype of ECs during the progression of HCC, which significantly existed in tumor tissue and closely related with senescence." (PMID 39674501, 2025). "We treated hBMVEC monolayers for 24 h with conditioned medium obtained over a 24 h period from the indicated tumor cells and then observed the distribution of VE-cadherin, JAM-A and claudin-5 expression by immunofluorescence imaging." (PMID 38570866, 2024). "IHC staining of junctional proteins showed that the immunofluorescence of Claudin-5, VE-Cadherin, Occludin, and JAM-A persisted during 7–21 dpi at both tumor core and margin." (PMID 37582846, 2023). "Significant differences in CLDN3, CLDN4, CLDN5, CLDN6, CLDN9, CLDN11, and CLDN12 expression were evident as a function of tumor stage." (PMID 35281827, 2022). "By IHC of CLDN5, exSFT/HPC revealed well-preserved vascular tight junctions that overlapped with CD34 expression on a background of diffuse immunoreactivity in tumor cells." (PMID 33799999, 2021). "HOXB9 overexpressed in tumor cells can destroy the integrity of the BBB by degrading junctional proteins (ZO-1, claudin-5, and VE-cadherin), and promote tumor cells to cross the BBB." (PMID 33411683, 2020). "To determine how tumor vessel normalization occurred in animal models, we identified changes in tumor vessels, pericytes, tight-junctional molecules by immunostaining for the markers α-SMA, Claudin-5 and VE-cadherin, respectively." (PMID 31656203, 2019). "In contrast, in tumor vasculature, high nuclear EZH2 staining paralleled a significant reduction in VEC and Claudin-5, whereas PECAM1 expression was unaltered (lower, and 8C)." (PMID 29233846, 2018). "When tumor cell conditioned and activated medium was used for stimulation, RBECs expressed fibronectin and SMA, and lost claudin-5 expression in a TGF-β dependent manner, as shown in our experiments." (PMID 25742314, 2015). "SP initiated changes in the localisation and distribution of tight junction proteins ZO-1 and Claudin-5, leading to increased permeability of the BBB, with SP antagonism reducing tumor cell migration via modulation of the BBB." (PMID 24818961, 2014). "In the tumor area, a strong signal of HGF and slight staining of VEGF wasdetected, while zonulin/prehaptoglobin-2 and claudin-5 strongly marked the cell borders ofsurrounding vessels (arrows)." (PMID 23637756, 2013). "In this study, we accurately discriminated samples that had a high tumor content from normal breast tissue based on the previous demonstration that FHL1 and CLDN5 can serve as such predictors." (PMID 16091131, 2005). "All 27 tumor samples were correctly qualified as cancerous tissues using the two-gene signature (FHL1 and CLDN5)." (PMID 16091131, 2005). "Similarly, the CD34+CLDN5+ cells (7.66 %) also existed in tumor tissue of HCC patients, and were hardly detected in the peri-tumor tissue of HCC patients." (PMID 39674501, 2025). "In tumor, more than half of CD34+CLDN5+ cells were senescent cell (55.0 %)." (PMID 39674501, 2025). "To this end, we used Cldn5 inhibitor (M01), which has been shown to open BBB in a tumor setting." (PMID 40408475, 2025). "The expression levels of CLDN5, 11, and 23 did not exhibit significant variations across the majority of tumor types." (PMID 41461671, 2025). "Therefore, the collective data suggest CD34+CLDN5+ ECs promoted the development of CCA and recruited MSCs into TME, with these ECs exhibiting elevated expression of IGF2 within the tumor." (PMID 39674501, 2025). "Studies have shown that 96% to 100% of AS express claudin-5, with strong and uniform staining throughout AS tumor, regardless of differentiation status." (PMID 40666093, 2025). "To test whether blocking Cldn5 would open BBB to plasma, we administered M01 in GL261 tumor-bearing Rab27-proficient mice followed by contrast enhanced magnetic resonance imaging (MRI)." (PMID 40408475, 2025).